CDT1 (chromatin licensing and DNA replication factor 1)
Diseases named in the same sentence as CDT1 in open-access papers (continued):
Sharing a sentence is not in itself a finding about the gene and the disease.
cancer (continued). "For example, overproducing CDT1 alone does not induce fast licensing in untransformed epithelial cells, so high levels of CDT1 cannot fully explain the fast licensing in iPSCs or some cancer cells." (PMID 37760529, 2023). "Moreover, the expression of CDT1 was observed in both the nuclei of cancer cells and in the nuclei of hepatocytes in noncancerous parenchyma." (PMID 36443564, 2022). "However, although the number of positive cells in these noncancerous hepatocytes was lower than in cancer cells, the expression of CDT1 in the nuclei was morphologically similar." (PMID 36443564, 2022). "However, we consider it essential to investigate the possibility of malignant transformation by overexpression of CDT1 in human hepatocyte cell lines rather than experimental systems using cancer cell lines." (PMID 36443564, 2022). "Furthermore, based on comparisons of CDT1 ΔCt among nonatypical hepatocytes, atypical hepatocytes and cancer cells in the same FFPE section, even within the same lobule, CDT1 expression was heterogeneous." (PMID 36443564, 2022). "It has been reported that the suppression of geminin, which is the specific protein inhibitor of CDT1, induces cell death in some, but not all, cancer cell lines, and also in some non-transformed cells, by inducing rereplication and activating the DNA damage checkpoint." (PMID 25115388, 2014). "Similar to the effect of the ubiquitination-resistant mutant of Geminin, expression of cancer-derived SPOP mutants also increased Cdt1 binding to MCM2, CDC6, and ORC2 but had no influence on Geminin binding to Cdt1." (PMID 34599168, 2021).
tumor (41 papers, 2006 to 2025). "The landscape indicated that high expression of CDT1 was associated with higher tumor purity, lower ImmunScore, lower ESTIMATEScore as well as higher pro-tumor related immune cells infiltration." (PMID 37790630, 2023). "Treatment with 33-11 or KH-4-43 in a panel of 36 tumor cell lines revealed cytotoxicity, which was linked to aberrant accumulation of Cdt1 known to trigger apoptosis." (PMID 34604860, 2021). "Cdt1 is deregulated in tumor specimens, while its aberrant expression is linked with aneuploidy and promotes tumorigenesis in animal models." (PMID 22479651, 2012). "CDT1 overexpression has been linked to lower survival and prognosis rates in several tumor forms." (PMID 37790630, 2023). "In addition, the high expression of CDT1 was significantly correlated with lower mast cells, and CD4 T cells expression, which indicated high expression of CDT1 was associated with a pro-tumor environment." (PMID 37790630, 2023). "Moreover, the transcriptional level of CDT1 in HCC samples was positively associated with clinical parameters such as clinical tumor stage." (PMID 34631549, 2021). "Targeting mutated Cdt1 had better efficacy for controlling the tumor." (PMID 35008270, 2021). "Therefore, mutated Cdt1 was the dominant neoantigen in these tumor cells." (PMID 35008270, 2021). "Aberrant CDT1 expression has been reported to promote tumourigenesis, and its small molecular inhibitor showed an obvious tumour-inhibition function by inducing DNA damage." (PMID 38728235, 2024). "Our study found six genes (PCNA, CDC6, CDC7, CDT1, CDK2, and RBBP8) that were most significantly linked with expression levels of key genes and tumor progression." (PMID 37656243, 2023). "Immunohistochemistry results indicated that the cytoplasmic staining level of CDT1 in tumor tissues is higher than that in adjacent normal tissues." (PMID 37790630, 2023). "In order to analyze the role of CDT1 expression in the tumor microenvironment (TME), the R ‘GSVA’ package and ‘ESTIMATE’ were used to analyze the relation among CDT1 expression, ESTIMATEScore, and immune infiltrates status." (PMID 37790630, 2023). "Downregulation of PCGEM1 or CDT1 inhibited the viability, promoted apoptosis and cycle arrest of PCa cells in vitro, and controlled tumor growth in vivo." (PMID 35412947, 2022). "There have been several reports on the relationship of CDT1 with carcinogenesis and tumor development." (PMID 36443564, 2022). "The accumulation of CDT1 regulates the DNA replication phenotype, thus affecting tumor cell replication and apoptosis." (PMID 35412947, 2022). "As expected, sh‐SIRT3 + oe‐NC treatment strikingly promoted tumor volume and weight relative to sh‐NC + oe‐NC, which was reversed by CDT1 overexpression." (PMID 33655712, 2021). "Inhibitors of E3 CRL4 33-11/KH-4-43 are toxic to a panel of tumor cells and such cytotoxicity can be partially reversed by depletion of Cdt1." (PMID 34604860, 2021). "According to pathological tumor grading criteria, patients with high-grade tumors tended to exhibit higher mRNA levels of CDT1 (p < 0.05)." (PMID 34631549, 2021). "The analysis of pevonedistat-treated tumor tissues showed a significant increase in p21 and CDT1 accumulation only in ACC-Meso-1-bearing mice." (PMID 33233664, 2020). "The proto-oncogenic effect of CDT1 involves its up-regulation and hyperactivity in DNA replication in malignant tumor cells or tissues." (PMID 31039152, 2019). "For example, the RT-PCR data showing increases in NAE-regulated gene transcripts and the tumor biopsy stains for the CRL substrates Cdt1 and Nrf-2 are supportive of the mechanism of action of NAE inhibition and subsequent CRL inactivation." (PMID 27056178, 2016).
tumor (continued). "CDT1 is overexpressed in many tumour derived cell lines and its overproduction can lead to carcinogenesis by inducing re-replication and chromosomal damage in normal cells." (PMID 25781993, 2015). "Our data suggest that treatment of tumor cells with commonly used chemotherapeutic agents induces differential responses with respect to Cdt1 proteolysis." (PMID 22479651, 2012). "Results showed that the tumor group had a higher CDT1 expression than the normal group." (PMID 37790630, 2023). "Understanding the molecular mechanisms by which CDT1 promotes tumor growth and metastasis could provide valuable insights for developing targeted therapies." (PMID 37790630, 2023). "The effects of SIRT3 and CDT1 were determined in the nude mice xenografted with the tumor." (PMID 33655712, 2021). "provided strong evidence that CDT1 can promote tumor development in vivo." (PMID 34631549, 2021). "Besides, our IHC staining results on HCC tissue microarray demonstrated that CDT1 expression in HCC tissues was significantly higher than that in paired adjacent non-tumor tissues." (PMID 34631549, 2021). "The accumulation of CDT1 concentration regulates DNA replication phenotype attributed to the loss of function of the NEDD8‐activating enzyme (NAE), thus, affecting the re‐replication and apoptosis in human tumor cells." (PMID 33655712, 2021). "Adapting the tumour cell growth environment from an anchorage-dependent to -independent one resulted in decreased Chk1 protein expression as well as decreased Cdc6, CDT1 and RRM2 protein expression." (PMID 27775084, 2016). "Overexpressed Cul4A may also contribute to genomic instability by degrading replication licensing factor CDT1 in tumour cells." (PMID 26218750, 2015). "Together, these results suggest that CDT1 may have a potential promoting role in tumor development." (PMID 34631549, 2021). "Similarly, high CDT1 expression was identified in a variety of tumor cells in the CCLE database." (PMID 34631549, 2021). "Recent studies have reported that some cases of aberrant DNA replication and uncontrolled cell cycle progression may be attributable to dysregulated CDT1, and its destructive role has been identified in the tumor initiation, development, and chemoresistance of some tumor types." (PMID 34631549, 2021). "Indeed, overexpression of Cdt1 and Cdc6 in mouse models has been shown to induce tumours." (PMID 22084381, 2011). "In our study, we identified four key genes (ALDH1A1, ASAH1, CDT1, and CDC45) that affect tumor cell stemness and lymph node metastasis." (PMID 38589907, 2024). "The results revealed that in tumor tissues from ccRCC patients, POLQ expression positively correlated with the expression of CDC6, CDC45, CDT1, FANCD2, and MCM2." (PMID 38270643, 2024). "In order to show the expression of CDT1 in LUAD more clearly, the TCGA database’s paired tumor and normal nearby samples, as well as the unpaired samples, were also studied using the two different statistical analysis techniques." (PMID 37790630, 2023). "Mechanistically, MLN4924 blocked the neddylation of cullins and induced accumulation of several tumor-suppressive substrates of Cullin-RING E3 ubiquitin ligases (CRLs), including CDT1, Wee1, p21, p27, Noxa, and p16." (PMID 27223074, 2016). "Our results showed that the tumor with higher CDC6 and CDT1 expression revealed more aggressive behavior." (PMID 19116018, 2008). "We only verified the expression level of CDT1 in tumor tissues and normal tissues, the absence of experimental validations using MALDI-TOF mass spectrometry or immunoblotting limited our understanding of the deep molecular mechanism." (PMID 37790630, 2023). "Although accumulating evidence suggests that CDT1 is a novel tumor biomarker, transcriptional analysis of CDT1 in human HCC has not been well documented." (PMID 34631549, 2021). "CDT1 and NRF2 protein levels were measured in tumor biopsies." (PMID 29594129, 2018).
tumor (continued). "Like CDC6, the ANOVA test revealed that there was no statistically significant overall correlation of CDT1 mRNA level with tumor size (p = 0.43), lymph node status (p = 0.200), clinical stage (p = 0.221) or histological grade (p = 0.215)." (PMID 19116018, 2008). "Research has shown that reducing CDT1 expression can significantly inhibit the malignant behavior of HCC cells, which indicates that USP37 may influence tumor progression by modulating the activity of CDT1 and other interacting proteins, requiring further investigation." (PMID 40926837, 2025). "However, in our study, although CDT1 expression showed significant differences in tumor stage and lymph node metastasis, there were no expression differences in tumor size and distant metastasis." (PMID 38589907, 2024). "The data showed that CDT1 was more highly expressed in the tumor group than in the normal group." (PMID 37790630, 2023). "Paired tumor tissues and normal tissues from two GEO datasets (GSE118370 and GSE140797) verified that CDT1 was upregulated in tumor tissues versus normal tissues, in addition, another cohort (GSE31210) indicated high expression level of CDT1 in LUAD sample compared to normal samples." (PMID 37790630, 2023). "Previous reports have shown that the overexpression of CDT1 and depletion of RPA1 could increase the activation of origin, induce DNA damage, stalled fork replication, defects in DNA damage repair, and promote genomic instability during tumor development." (PMID 34893582, 2021). "Alternatively Hela cells are tumour derived while S2 cells are not and this may also lead to some differences in the response of the cells to replication perturbation similar to that reported for cdt1 overexpression in Hela cells vs fibroblasts." (PMID 22102875, 2011).
infection (5 papers, 2010 to 2024). The state of being infected such as from the introduction of a foreign agent such as serum, vaccine, antigenic substance or organism. "In contrast, Cdt1 increased with proteasome inhibition in both mock and BKPyV-infected cells, suggesting that SCFSkp2 was active and Cdt1 was degraded during a BKPyV infection." (PMID 39636788, 2024). "We showed that Cif increases the half-life of Cdt1, thus providing a mechanistic link for the DNA re-replication that occurs in a fraction of HeLa cells 2 or 3 days post-infection." (PMID 20941356, 2010). "Interestingly, transcript levels of genes regulating DNA replication and cell cycle progression (Cdc25c, Fosb, Cdkn3, cyclin E2, Chaf1b, Cdt1) were specifically increased in SkMCs and neurons after infection." (PMID 28775382, 2017). "In this study, we have used siRNA knockdowns of Cdc6, Cdt1, ORC2 and MCM7 to address their role, if any, in HCMV DNA replication and show that infection of cells depleted for these proteins results in enhanced viral lytic DNA replication." (PMID 22586460, 2012). "Consequently, we next asked whether removal of cellular proteins such as Cdt1 and Cdc6, which are responsible for licensing cellular replication origins by recruiting MCM proteins, had any effect on infection." (PMID 22586460, 2012).
autosomal recessive disease (2 papers, 2019 to 2024). Autosomal recessive form of disease. "The regions of heterozygosity involved two genes associated with autosomal-recessive diseases, CDT1, located at 16q24.3, and ALG1, located at 16p13.3." (PMID 31391865, 2019).
hematological malignancies (1 paper, 2017). "Preclinical studies with BET inhibitors demonstrated attractive anticancer activities through suppression of aberrantly activated oncogenic factors, such as cMyc, p27, cdt1 in hematological malignancies." (PMID 29290992, 2017).
CDT1 also shares sentences with these, for which no sentence is quoted: primordial dwarfism (3 papers); dwarfism (2); Werner syndrome (2); acute myeloid leukemia (1); Bloom syndrome (1); chronic myelogenous leukemia (1); Cockayne syndrome (1); Fanconi anemia (1); glioblastoma (1); Gorlin syndrome (1); infectious disease (1); liver (1); malaria (1); mastitis (1); Meier-Gorlin syndrome 4 (1); melanoma (1); microcephaly (1); Patellar aplasia (1); renal cell carcinoma (1); sickle cell anemia (1); skin melanoma (1); squamous cell carcinoma of (1); stomach adenocarcinoma (1); xeroderma pigmentosum (1).